ATP1A3 (ATPase Na+/K+ transporting subunit alpha 3)
Diseases named in the same sentence as ATP1A3 in open-access papers (continued):
Sharing a sentence is not in itself a finding about the gene and the disease.
Rapid-onset dystonia-parkinsonism (35 papers, 2011 to 2024). Rapid-onset dystonia-parkinsonism (RDP) is a very rare movement disorder, characterized by the abrupt onset of parkinsonism and dystonia, often triggered by physical or psychological stress. "Rapid-onset dystonia parkinsonism (RDP) is a rare disease caused by ATP1A3 mutation with considerable clinical heterogeneity." (PMID 35978945, 2022). "This included the α3 subunit of Na+/K+ ATPase (ATP1A3), in which mutations have been associated with several neurologic conditions, such as rapid-onset dystonia parkinsonism." (PMID 31461916, 2019). "Autosomal dominant mutations in ATP1A3 have been linked to rapid-onset dystonia parkinsonism, alternating hemiplegia of childhood, and CAPOS syndrome, with more than 80 different disease-associated mutations reported, many of which target ion binding sites." (PMID 30623173, 2018). "Mutations in ATP1A3 produce rapid-onset dystonia-parkinsonism (RDP); alternating hemiplegia of childhood (AHC), and severe infantile epilepsy." (PMID 26990090, 2016). "ATP1A3 mutations can cause rapid-onset dystonia-parkinsonism (RDP) with a similar age and speed of onset, as well as severe diseases of infancy." (PMID 26990090, 2016). "Rapid-onset dystonia-parkinsonism (RDP) is a movement disorder associated with mutations in the ATP1A3 gene." (PMID 24803225, 2014). "Rapid-onset dystonia-parkinsonism (RDP) is a rare disease associated with mutations in the ATP1A3 gene, located on chromosome 19." (PMID 24803225, 2014). "Other mutations in ATP1A3 have previously been demonstrated to cause rapid-onset dystonia-parkinsonism (also called dystonia-12) or alternating hemiplegia of childhood." (PMID 24468074, 2014). "Genetic studies have identified that mutations in ATP1A3 are linked with rapid-onset dystonia Parkinsonism in humans." (PMID 22662178, 2012). "ATP1A3 has been implicated in rapid-onset dystonia parkinsonism (RDP), characterized by sudden onset of neurological symptoms over hours to a few days, suggesting a role in the sudden onset of behavioral changes like during estrus." (PMID 21504592, 2011). "Interestingly, mutations in the ATP1A3 gene are known to cause rapid-onset dystonia parkinsonism." (PMID 30623173, 2018). "Rapid-onset dystonia-parkinsonism (RDP, DYT12) is a rare autosomal dominant movement disorder with variable expressivity and reduced penetrance that is caused by a mutation of ATP1A3 (Na+/K+ −ATPase α3 subunit gene) located on chromosome 19." (PMID 27835968, 2016). "In an extended case-control study, we have demonstrated the potential of IR-Na MRI in detecting pathophysiological changes in a patient suffering from a mutation in the alpha 3 subunit gene of the sodium/potassium pump (ATP1A3), resulting in a disease named Rapid-Onset Dystonia Parkinsonism." (PMID 35885033, 2022). "Then, we briefly highlight key P-type ATPases involved in neuronal disorders such as the copper transporters ATP7A (Menkes disease), ATP7B (Wilson disease), the Na+/K+-ATPases ATP1A2 (familial hemiplegic migraine) and ATP1A3 (rapid-onset dystonia parkinsonism)." (PMID 24904274, 2014). "As far as psychomotor deterioration is concerned, we assume that a genetic determinant could be involved considering that severe deterioration with no recovery is typical of Rapid Onset Dystonia Parkinsonism, another allelic disorder caused by the ATP1A3 mutation." (PMID 33897609, 2021).
epilepsy (23 papers, 2014 to 2024). A brain disorder characterized by episodes of abnormally increased neuronal discharge resulting in transient episodes of sensory or motor neurological dysfunction, or psychic dysfunction. "We think this review timely introduces the potential contribution of ATP1A3 mutations in both the genesis and progression of epilepsy." (PMID 36866063, 2023). "The authors reported on early life epilepsy with episodic apnea potentially secondary to ATP1A3 mutation in a Tunisian child." (PMID 36866063, 2023). "The authors reported a neonatal case of catastrophic early life epilepsy, associated with a novel heterozygous mutation in the ATP1A3 gene, a single amino acid deletion in the 8th transmembrane domain of ATP1a3 (F913del)." (PMID 36866063, 2023). "With increased clinical findings, it is somehow convincible that epilepsy with ATP1A3 mutation shares a high incidence of being pharmacoresistant." (PMID 36866063, 2023). "Our current review highlights that inactivating mutation of ATP1A3 is a plausible mechanism for human epilepsy due to the high degree of similarity between the various Na+/K+-ATPase isoforms of mice and humans." (PMID 36866063, 2023). "Evidences have been found linking a common variation of ATP1A3 (ATP1A3 rs8107107) to a higher risk of developing epilepsy, and in particular, epilepsy with generalized tonic-clonic seizures." (PMID 36866063, 2023). "Those patients were reported to have concomitant epilepsy (pediatric case of catastrophic early life epilepsy), especially in those with mutations in p.Glu815Lys, p.Gly358Val, and p.Ile363Asn of ATP1A3." (PMID 35751846, 2022). "By meaning ATP1A3 mutation, epilepsy was more frequent in cases with p.Glu815Lys mutation (89%, 8/9), in respect to 60% (6/10) with p.Asp801Asn and about 53% (9/17) with other mutations (p = 0.09 compared to the p.Glu815Lys mutation group)." (PMID 33897609, 2021). "Recently, two children with catastrophic early life epilepsy were shown to carry novel ATP1A3 mutations." (PMID 27378932, 2016). "In an infant with catastrophic epilepsy and p.Gly358Val ATP1A3 mutation that severely inhibited the ATPase, cerebellar atrophy was among the neuropathological findings." (PMID 26990090, 2016). "This mutation corresponds to I810N in human ATP1A3, and one patient in our cohort (A00403) who carried this mutation did exhibit epilepsy." (PMID 24842602, 2014). "Then, some possible mechanisms of how ATP1A3 mutations result in epilepsy are provided." (PMID 36866063, 2023). "Although previous research has linked ATP1A3 mutations to the most severe form of infantile epileptic encephalopathy, however, the precise affected brain area of ATP1A3-related epilepsy currently remain unknown." (PMID 36866063, 2023). "Such mutation could cause severe phenotypes of ATP1A3-related disorder spectrum that include catastrophic early life epilepsy." (PMID 36866063, 2023). "Epilepsy is currently demonstrated to be one consequence of ATP1A3 alteration; however, whether epilepsy could be also a cause of ATP1A3 alteration still need more research." (PMID 36866063, 2023). "In addition to those PWEs whose epilepsy was directly caused by the mutation in the ATP1A3 isoform, patients with other ATP1A3-associated neurological diseases are also reported to be at high risk for concomitant seizures." (PMID 36866063, 2023). "The existence of ATP1A3 mutations in epilepsy seems to be the “elephant in the room”." (PMID 36866063, 2023). "Predictions regarding the factors in the epilepsy disease severity of ATP1A3 mutations can be made, and at least four ways things may go wrong." (PMID 36866063, 2023). "Although decreased activity may play a role, a molecular foundation for the epilepsy-promoting effects of ATP1A3 mutations is yet unknown." (PMID 36866063, 2023). "The following studies further demonstrated that severe epilepsies have been reported in people with ATP1A3 mutations, and intellectual impairment may concomitantly occur with FHM and AHC." (PMID 36866063, 2023).
epilepsy (continued). "Similarly, a reduced activity of ATP1A3, a Na-K ATPase that is mainly expressed in cortical interneurons, has been associated with a severe developmental disability including epilepsy and postnatal microcephaly." (PMID 35883578, 2022). "The impact of ATP1A3 mutation on epilepsy prevalence may partly be mediated via these mechanisms." (PMID 36866063, 2023). "Based on the clinical evidence, we have already recognized the potential roles of ATP1A3 in the incidence of epilepsy clinically." (PMID 36866063, 2023). "Here, we mainly focus on the specific functions of ATP1A3 in epilepsy which is a common and intractable chronic neurological disease." (PMID 36866063, 2023). "In this review, we focused on the role of ATP1A3 alterations in epilepsy, followed by potential mechanisms, by summarizing both clinical and laboratory findings." (PMID 36866063, 2023). "Based on current research, more efforts should be directed toward launching more large-scale clinical research to further explore ATP1A3 alteration significance in the incidence of epilepsy, disease severity, or other specific clinical characteristics." (PMID 36866063, 2023). "Delighted by related findings from both clinical and laboratory aspects, in this review, the alterations of ATP1A3 in epilepsy were initially introduced, followed by some related mechanisms." (PMID 36866063, 2023). "Their patient's clinical path and the success of KD imply the possibility of using this approach to treat ATP1A3-related epilepsy or other disorders." (PMID 36866063, 2023). "For example, EA and epilepsy associations include EA1 (KCNA1), EA2 (CACNA1A), EA5 (CACNB4), EA6 (SLC1A3), SCN2A, KCNA2, ATP1A3, SLC2A1, and PRRT2." (PMID 37008993, 2023). "Although somehow limited direct data have been presented, various clinical evidence could still support the essential roles of ATP1A3 in the incidence of epilepsy." (PMID 36866063, 2023). "However, the precise mechanisms regarding the roles of ATP1A3 in the drug sensitivity of epilepsy still need more evidence." (PMID 36866063, 2023). "Summary of clinical findings involving ATP1A3-related epilepsy." (PMID 36866063, 2023). "Generally speaking, these mutation-related phenotypes could provide more optimized animal models for exploring the roles of ATP1A3 in epilepsy, and furthermore, could provide a useful platform for screening effective treatments of certain epileptic phenotypes." (PMID 36866063, 2023). "Besides clinical investigations, animal studies provide great platforms for both intervention convenience and in-depth mechanism insights for addressing the role of ATP1A3 as well as Na+-K+-ATPase in epilepsy from the bench side." (PMID 36866063, 2023). "The type and severity of epilepsy in ATP1A3-related disease can vary greatly." (PMID 33833732, 2021). "Mutations in the gene ATP1A3 encoding the α3 isoform have been discovered in patients with rapid-onset dystonia parkinsonism (RDP), alternating hemiplegia of childhood (AHC), and early life epilepsy." (PMID 27148079, 2016). "The beginning of related studies can be traced back to the 2000s, and various early explorations have indicated the important roles of ATP1A3 in epileptogenesis and epilepsy, and have tried to elucidate the precise mechanisms, although most of which were theoretical speculation." (PMID 36866063, 2023). "However, most current papers on pharmaco-resistant epilepsy associated with ATP1A3 mutations did not provide any tips on how to manage seizures." (PMID 36866063, 2023). "This might be the reason why ATP1A3-related epilepsy usually shows a worse prognosis." (PMID 36866063, 2023). "Furthermore, the link between ATP1A3-disease mutations and epilepsy was observed in a Chinese 12-year old boy with the I810N mutation, who was reported to have AHC with developmental delay and epilepsy." (PMID 27378932, 2016).
CAPOS syndrome (10 papers, 2014 to 2024). "ATP1A3 p.E818K has been regarded as a causal mutation of CAPOS syndrome since identified in 2014, long after the initial description in 1996." (PMID 34692702, 2021). "In collaboration with our study, a recent study also demonstrated evidence for ANSD in most subjects with CAPOS syndrome caused by ATP1A3 p.Glu818Lys." (PMID 32899707, 2020). "Another de novo, recurring variant p.Glu818Lys in ATP1A3, which causes enigmatic perilingual/postlingual ANSD and is sometimes accompanied by CAPOS syndrome, was also included in this kit, making this kit an exceptionally efficient and accurate screening tool for Korean ANSD children." (PMID 32899707, 2020). "In addition, all of the ATP1A3 mutations associated with DYT12 or AHC that have been assessed functionally produce loss of function, while the recurrent c.2452G > A variant found in the three CAPOS syndrome families presented here has characteristics of a gain-of-function mutation." (PMID 24468074, 2014).
developmental delay (9 papers, 2017 to 2024). "Individuals with heterozygous loss-of-function ATP1A3/ Na/K ATPase α3 variants display developmental delay, postnatal microcephaly, spasticity, axial hypotonia, and learning deficits." (PMID 39103699, 2024). "The patient had an unreported heterozygous de novo sequence variant in ATP1A3, and have been found to be of a phenotype characterized by early-onset attacks of movement disorders, which proved to be epileptic, and severe developmental delay." (PMID 36866063, 2023). "The starting point of this study differed in that patients were recruited based on the detection of ATP1A3 variants within a WES study aimed at using advanced genomics to diagnose individuals with previously undiagnosed developmental delay." (PMID 36192182, 2022).
Alzheimer disease (8 papers, 2014 to 2025). A progressive, neurodegenerative disease characterized by loss of function and death of nerve cells in several areas of the brain leading to loss of cognitive function such as memory and language. "Furthermore, single particleanalysis of plasma from patients with Alzheimer's disease indicateshigher amyloid-β positivity in ATP1A3+ EVs, suggestingthey provide better diagnostic prediction than that of other plasmabiomarkers." (PMID 40720603, 2025). "In addition, the presence of AD changes in all four gene carriers raises the question as to whether the mutation in the ATP1A3 gene represents a risk factor for the development of Alzheimer disease." (PMID 24803225, 2014). "ATP1A3+ EVs isolated from plasma from individualswith Alzheimer's disease demonstrated amyloid-β positivity,providing superior diagnostic accuracy compared to conventional plasmabiomarkers." (PMID 40720603, 2025). "Proteomic analysis of immunoprecipitated ATP1A3+ brain-derived EVs reveals a greater enrichment of synapticmarkers and Alzheimer-disease-related cargo proteins than that ofNCAM1+ or L1CAM+ EVs." (PMID 40720603, 2025). "The age-related ATP1a3 mRNA reduction seemed to be faster in Alzheimer’s disease patients compared to control aged-patient and precedes diffuse plaque apparition." (PMID 38796484, 2024). "In human adult brain, ATP1a3 appeared also to be defective in Alzheimer’s disease, a brain pathology involving impaired autophagy as others proteinopathies." (PMID 38796484, 2024). "Seizures are commonly observed in ATP1A2- and ATP1A3-related neurological disorders, and in a mouse model of Alzheimer’s diseases, seizures are exaggerated by low ASC levels." (PMID 33544780, 2021). "Studies have shown CSF proteome changes similar to Alzheimer's disease during chemotherapy, including increases in Apolipoprotein E (APOE) and Calsyntenin-1 (CLSTN1), and decreases in Sodium/potassium-transporting ATPase subunit alpha-3 (ATP1A3), linked to several neurological disorders." (PMID 38350915, 2024). "More recent studies revealed that the amyloid-β plaques could bind to ATP1a3 and block its activity, suggesting that this interaction is partly responsible of neuronal degeneration in Alzheimer’s disease." (PMID 38796484, 2024). "On the contrary of ATP1a3, ATP1a1 expression did not seem to be affected in Alzheimer’s disease patients." (PMID 38796484, 2024). "In Alzheimer's disease (AD), there is reduced expression of Atp1a3 but not Atp1a1 in the frontal cortex of AD patients as well as impaired NKA activity." (PMID 30623173, 2018).